NDRG1 (N-myc downstream regulated 1)
Diseases named in the same sentence as NDRG1 in open-access papers (continued):
Sharing a sentence is not in itself a finding about the gene and the disease.
retinoblastoma (1 paper, 2013). A malignant tumor that originates in the nuclear layer of the retina. "Within the recurrent focal gains or losses in the RbTKO retinoblastoma model, we found 12 in cancer genes, including Lmo1 in 5/6 samples; Ndrg1, Brd4, Fbxo11, and Rbm15 in 4/6 samples; Mdm4, Msi2, and Ezh2 in 3/6 samples." (PMID 23765217, 2013).
Sepsis (1 paper, 2025). Sepsis is defined as life-threatening organ dysfunction caused by a dysregulated host response to infection. "These genes could be diagnostic markers for predicting ARDS in sepsis patients, with NDRG1 showing a causal link to ARDS." (PMID 39854144, 2025). "Our study identified DE‐PRGs—NDRG1, DDX3X, PTPRC, and TNFSF8—in patients with sepsis‐associated ARDS." (PMID 39854144, 2025). "Immunohistochemical analysis revealed that NDRG1 is predominantly localized around blood vessels, exhibiting heightened expression in the sepsis ARDS group, accompanied by notable perivascular inflammatory cell infiltration." (PMID 39854144, 2025). "In a mouse model of sepsis, suppression of NDRG1 alleviated lung injury." (PMID 39854144, 2025). "This study identifies four key PANoptosis‐related genes (NDRG1, DDX3X, PTPRC, and TNFSF8) that are differentially expressed in sepsis and septic ARDS." (PMID 39854144, 2025). "Our findings suggest that PANoptosis may contribute to immune dysregulation in sepsis‐related ARDS, positioning NDRG1 as a potential target for developing ARDS treatments." (PMID 39854144, 2025).
stomach adenocarcinoma (1 paper, 2023). "The low SYK expression (p = 2.895 × 10−3), NDRG1_pT346 (p = 3.872 × 10−2), P90RSK (p = 1.991 × 10−3), and TIGAR (p = 2.885 × 10−4) and the high XBP1 expression (p = 8.621 × 10−4) were significantly positively associated with the poor overall survival of STAD (stomach adenocarcinoma) patients." (PMID 36979962, 2023).
testis cancer (1 paper, 2024). "Almost all of the top-performing genes were that of over-expression, with PMS2 in THYM; CARD11, LASP1, STIL, POLE, KMT2C, and CLIP1 in testis cancer; ERC1, WRN, OLIG2, FANCC, and ACSL6 in ACC; and SOX2 and NDRG1 in ESCA leading in performance with AUCs ranging 0.832-0.911." (PMID 38491101, 2024).
urothelial carcinoma (1 paper, 2024). A malignant neoplasm derived from the transitional epithelium of the urinary tract (urinary bladder, ureter, urethra, or renal pelvis). "This study aimed to investigate the role of intra-tumor MVD (as a surrogate measure of angiogenesis), VM, and NDRG1 in urothelial carcinomas." (PMID 38561462, 2024). "Positive NDRG1 expression was detected in 50/60 (83.3%) of urothelial carcinoma specimens." (PMID 38561462, 2024). "Also, the exact mechanism by which NDRG1 can affect tumor angiogenesis and VM formation in urothelial carcinoma requires further investigations." (PMID 38561462, 2024). "This study aimed at assessing the role of intra-tumor MVD (as a surrogate measure of angiogenesis), VM, and NDRG1 in urothelial carcinomas and their correlation with different clinicopathologic features, then assessing the correlation between VM, MVD, and NDRG1 in urothelial carcinomas." (PMID 38561462, 2024). "Therefore, further prospective studies using larger sample size are recommended to evaluate the effects of MVD, VM, and NDRG1 on the survival of urothelial carcinoma patients." (PMID 38561462, 2024). "In conclusion, the current results suggested that MVD, VM, and NDRG1 expression may serve as poor prognostic markers for urothelial carcinoma." (PMID 38561462, 2024). "However, the role of NDRG1 and its correlation with tumor angiogenesis and VM in urothelial carcinoma have not been extensively studied and remain to be further clarified." (PMID 38561462, 2024). "The role of NDRG1 in urothelial carcinoma has not been extensively investigated." (PMID 38561462, 2024). "No previous study assessed the correlation between NDRG1 and MVD in urothelial carcinoma." (PMID 38561462, 2024).
Ventricular hypertrophy (1 paper, 2025). Enlargement of the cardiac ventricular muscle tissue with increase in the width of the wall of the ventricle and loss of elasticity. "Another study reported that NDRG1 regulates ferroptosis and iron metabolism in cardiomyocytes, mitigating Ang II-induced ventricular hypertrophy and fibrosis." (PMID 40158182, 2025).
tumor (287 papers, 2004 to 2026). "Subsequently, we utilized extensive genetic data from clinical patients, integrated with genome‐wide association studies (GWAS), to identify NDRG1 as a key gene and validated its causal relationship with tumor progression through Mendelian randomization (MR)." (PMID 40539245, 2025). "In pathological contexts, NDRG1 is considered an independent prognostic marker in different tumour types, and NDRG1 gene mutations have been identified as causal factors of genetic diseases." (PMID 40332138, 2025). "A strong trend was demonstrated where NDRG1 was linked to tumor aggressiveness features being most amplified in the basal-like subtype (36%), followed by the HER2+ (25%) and luminal A (2.8%) subtypes." (PMID 40378957, 2025). "Upregulation of NDRG1 expression was associated with better differentiation but also indicated advanced tumor stage and poor prognosis." (PMID 40151835, 2025). "NDRG1 expression across tumour grades also indicated an association of NDRG1 high expression with higher tumour grade." (PMID 40530439, 2024). "The protein level expressions of VEGFR2 and NDRG1, the markers associated with angiogenesis and tumour metastasis, were significantly upregulated in low‐Ki67 expression group compared to high‐Ki67 expression in the TCPA‐LUSC database (p < 0.05)." (PMID 39021279, 2024). "N-myc downstream-regulated gene 1 (NDRG1), encoding a growth and cancer related protein, was confirmed to be overexpressed in lung tumor tissues and correlated with tumor angiogenesis in LUAD patients." (PMID 38182978, 2024). "The molecular mechanism of action of NDRG1 is mediated via its association with other proteins such as the tumor suppressor, mitogen-inducible gene-6 (MIG6), leading to MIG6 stabilization that downregulates EGFR via a lysosomal degradation mechanism." (PMID 38815861, 2024). "Phosphorylation of NDRG1 at Thr346 (among other sites) was proposed as pro-oncogenic in certain cell types where NDRG1 promotes tumor progression 11, and it has been associated with oncogenic markers such as mTORC2 activation 20,28 and PTEN depletion." (PMID 36594086, 2023). "The meta-analysis results revealed a positive correlation between NDRG1 protein expression and lymph node status, suggesting that increased NDRG1 protein expression is associated with an increased spread of the tumor to the lymph nodes." (PMID 37858101, 2023). "NDRG1 exhibited a strong association with poor clinical outcomes and tumor characteristics associated with an aggressive phenotype." (PMID 37858101, 2023). "The downregulation of NDRG1 is associated with enhanced organ-specific tumor growth in breast, colon, prostate, cervical, ovarian, and pancreatic tissues." (PMID 37345116, 2023). "The study concluded that increased NDRG1 protein expression was associated with increased metastasis of the tumor to the axillary lymph node." (PMID 37858101, 2023). "Some studies have reported a significant direct association between NDRG1 and tumor grade, as well as axillary lymph node metastasis." (PMID 37858101, 2023). "Elevated levels of NDRG1 protein were observed to have an association with the metastasis of the tumor to the axillary lymph nodes, indicating a potential link to aggressive tumor characteristics." (PMID 37858101, 2023). "We defined the clinical role of NDRG1 as an oncogene because it is overexpressed in tumor tissues and is associated with poor prognosis in patients with HNC." (PMID 35563887, 2022). "On the basis of the results of available datasets, we found that NDRG1 silencing was associated with various tumor biological functions such as RNA splicing, histone modification, and peptidyl-lysine modification." (PMID 36686830, 2022).
tumor (continued). "Previous studies have implicated tumor suppressor NDRG1 in mediating iron chelation mechanism of action through the inhibition as EGFR, TGF-β, and STAT3." (PMID 36213122, 2022). "The risk ratio of NDRG1, an important marker from tumour cluster B, was 1.309 (95% CI = 1.147–1.493, P < 0.001)." (PMID 35109839, 2022). "While NDRG1 was contributing to tumour suppression following loss of TBX2/CoREST, a number of other target genes (potentially novel TSGs) were likely involved in this phenotype and therefore warranted further investigation." (PMID 35687133, 2022). "The N-myc downstream-regulated gene (NDRG1–4) family, a hypoxia-associated protein, has been involved in cell proliferation and differentiation, stress responses, tumor progression, and metastasis." (PMID 35795037, 2022). "Initial studies showed NDRG1 to be associated with cell differentiation in normal and tumour tissues." (PMID 36497221, 2022). "Recent evidence indicated that NDRG1 exerted its favourable function by modulating a trail of tumour progression associated signalling pathways in multiple human cancers." (PMID 34965023, 2021). "For example, the downregulation of NDRG1 is associated with tumor metastasis via inducing epithelial-mesenchymal transition; the expression of PPP2R1B was regulated by miRNA-587 to antagonizes 5-FU-induced apoptosis in CRC." (PMID 34233675, 2021). "In ESCC, NDRG1 abundance in carcinoma cells was reported to be significantly associated with less pronounced tumor invasion." (PMID 32106831, 2020). "It is interesting to note that NDRG1 is a known tumor suppressor that has been reported to be associated with stress and the prevalence of hypoxic conditions in tumors." (PMID 32974197, 2020). "Loss of NDRG1 has been consistently linked to tumor progression and metastasis, as well as to poor survival of breast and prostate cancer patients." (PMID 32023813, 2020). "Decreased NDRG1 levels in these neoplasms is associated with a poor prognosis, possibly explained by the ability of NDRG1 to inhibit epithelial-mesenchymal transition (EMT)." (PMID 31029158, 2019). "Having demonstrated that NDRG1 was inversely associated with tumor size in clinical samples, we then aimed to explore the underlying mechanisms." (PMID 29137287, 2017). "Correlation analysis showed that the expression of NDRG1 in HCCs was significantly associated with tumor size and differentiation, PARP1 with tumor size and stage (p < 0.05)." (PMID 26883192, 2016). "More importantly, over-expression of NDRG1 was significantly and positively associated with aggressive tumor features such as high AFP levels (400 ng/ml), advanced stages, vascular invasion, dedifferentiation, metastasis, recurrence, and poor survival rates." (PMID 26359353, 2015). "A previous study demonstrated that the downregulation of NDRG1 is significantly associated with a higher World Health Organization tumor grade, and a worse overall survival rate." (PMID 25777142, 2015). "These roles have been implicated in mediating, in part, the anti-tumor and anti-metastatic activities of the potent thiosemicarbazones, Dp44mT or DpC, due to the ability of these compounds to markedly up-regulate NDRG1." (PMID 26125440, 2015). "A tumor-promoting role has also been reported for NDRG1, and it has been implicated in metastasis suppression." (PMID 24498060, 2014). "Together, these results suggest that NDRG1 is a tumor suppressor gene in various human cancers and the mechanism of NDRG1 gene expression loss needs to be investigated." (PMID 23899187, 2013).
tumor (continued). "N-myc downstream-regulated gene 1 (NDRG1) has been reported to be a multifunctional protein associated with carcinogenesis and tumor progression." (PMID 24260043, 2013). "Tumor size (p = 0.044), pT (p = 0.006), pN (p = 0.014), clinical stage (p = 0.000) and NDRG1 (p = 0.000) were considered to be independent risk factors for recurrence." (PMID 23874544, 2013). "Furthermore, high expression of NDRG1 is closely associated with poor prognosis in various cancers, supporting its potential role in tumor progression." (PMID 40539245, 2025). "In cancer, the probability of NDRG1 mutations occurring in tumours is low." (PMID 40332138, 2025). "However, in other tumors such as hepatocellular carcinoma, oral squamous cell carcinoma, nasopharyngeal carcinoma, osteosarcoma, and non-small cell lung cancer, upregulation of NDRG1 is often associated with poor tumor outcomes." (PMID 39668822, 2024). "More recently, the mTOR/AKT pathway was implicated in the regulation of NDRG1 as a tumor/metastasis promoter, and TGFβ has also been found to be responsible for NDRG1 having tumor-promoting activity via regulation of the epithelial–mesenchymal transition, metastasis, and cancer stem cells." (PMID 38611020, 2024). "However, accumulating evidence indicates that the presence of NDRGs, particularly NDRG1, is negatively correlated with patient prognosis and is associated with increased tumor progression and metastasis in various types of cancer." (PMID 38611020, 2024). "NDRG1 down-regulation was associated with higher tumor grade, stage, and lymphatic invasion." (PMID 38561462, 2024). "However, in osteosarcoma models, up-regulation of NDRG1 has been associated with higher rate of tumor growth." (PMID 37249826, 2023). "Various reports have linked the expression of NDRG1 with suppressing tumor growth and development." (PMID 37970212, 2023). "Accordingly, we further investigated the protein expression of p-NDRG1 (Thr346) in TNBC tumor tissue and whether it was associated with patient survival." (PMID 36594086, 2023). "NDRG1 is a tumour-associated gene that belongs to the superfamily alpha/beta hydrolases." (PMID 37377864, 2023). "Our study found seven downstream factors that may be associated with chemoresistance, LTF, SOD2, STAT1, CDKN2A, CD81, RAC1, and NDRG1 and five factors that may be associated with tumor development, CCN1, DCTN3, MUC1, H1-5, and SLC1A5." (PMID 35421932, 2022). "Thus, our findings provide novel insights suggesting that loss of NDRG1 leads to a decrease in actin‐mediated cellular motility but an increase in cellular invasion, resulting in increased tumor dissemination which positively impacts metastatic outcome." (PMID 28371345, 2017). "We further examined whether tumor-associated macrophages could produce potent angiogenic factors as well as whether they have M1- and/or M2-specific characteristics in Ndrg1 KO mice." (PMID 26778110, 2016). "However, discrepant results have been obtained regarding a possible association of NDRG1 with tumor progression." (PMID 26965928, 2016). "Our data allows us to further understand the biological processes underlying NDRG1-associated tumor aggressiveness, and also suggests new avenues for developing therapeutic approaches for HCC, such as through the disruption of NDRG1 interaction with GSK-3β and/or Nur77." (PMID 26359353, 2015). "In recent years, NDRG1 has been described as a potential tumor suppressor gene in various human cancers, and may be associated with tumor aggressiveness and metastasis." (PMID 23874837, 2013). "Association of NDRG1 with clinicopathological criteria in tumor-related “death group”." (PMID 23874544, 2013).